STAT3 (signal transducer and activator of transcription 3)
Diseases named in the same sentence as STAT3 in open-access papers (continued):
Sharing a sentence is not in itself a finding about the gene and the disease.
lung adenocarcinoma (continued). "For example, Cucurbitacin I (a typical terpenoid) might inhibit the phosphorylation of STAT3 and enhance the phosphorylation of STAT1 in A549 lung adenocarcinoma cells by disrupting actin filaments." (PMID 36559280, 2022). "This study showed that treatment with ubenimex alone or combined with pemetrexed could considerably increase the expression level of SOCS1 in patients' serum, lung adenocarcinoma cells, and mouse tumor tissues and inhibit the JAK2/STAT3 signaling pathway." (PMID 35789603, 2022). "With inhibition of inhibiting the JAK/STAT3 signalling pathway by STAT3 inhibitors, we found IFNγ-JAK-STAT1 pathway activation by IFNγ could further keep lung adenocarcinoma cells from proliferation and promote its apoptosis." (PMID 36185620, 2022). "AZD1480 is another JAK1/2 tyrosine kinase inhibitor that has shown promising anti-tumor efficacy in an EGFR-driven model of lung adenocarcinoma by inhibiting STAT3 signaling but lacked overall clinical activity in human NSCLC patients (NCT01219543)." (PMID 34944848, 2021). "In conclusion, this study presents the pivotal finding that low expression of SOCS2 induces invasion and metastasis of human lung adenocarcinoma cells by regulating EMT both in vitro and in vivo, which is mainly dependent on the IGF1/IGF1R-stimulated STAT3 or STAT5 pathway." (PMID 29559623, 2018). "STAT3 phosphorylation inhibitor (Cryptotanshinone, MCE, USA) suppressed STAT3 (Tyr705) phosphorylation and then downregulated Bcl-2 and Survivin expression in lung adenocarcinoma cells." (PMID 27922075, 2016). "The results showed that metformin treatment could significantly reduce IL-6-induced STAT3 phosphorylation in A549, HCC827 and HCC827-pSB388 lung adenocarcinoma cells in a dose-dependent manner." (PMID 24789104, 2014). "In lung adenocarcinomas, STAT3 is one of the most important signaling mediators in both normal and EGFR-mutated tumors." (PMID 25763322, 2014). "The human lung adenocarcinoma cell line, A549, was treated with IL-27 at time points from 0.25 to 72 hours and analyzed for activated or tyrosine phosphorylated STAT1 (P-STAT1) and STAT3 (P-STAT3) proteins by Western blot." (PMID 24274066, 2013). "For example, the inhibition of mutant-EGFR in lung adenocarcinoma cells or mutant-BRAF in thyroid cancer cells was shown to induce the secretion of IL6 and the subsequent activation of STAT3, and in both cases, blocking the STAT3 function largely prevented the emergence of drug-tolerant cells." (PMID 38473364, 2024). "In the second cohort, we performed IHC analysis of CD47 and p-STAT3 expression in an in-house–generated tissue microarray containing paired tumor samples and adjacent normal tissue samples from 12 patients with KRASMUT lung adenocarcinoma and 28 patients with KRASWT lung adenocarcinoma." (PMID 36413402, 2023). "In summary, our research illustrates that FIBP interacts with STAT3 to increase its phosphorylation, thereby enhancing its transcriptional activity and inducing the expression of its target gene EME1, which ultimately contributes to lung adenocarcinoma progression and radioresistance." (PMID 37564211, 2023). "In addition, STAT3 inhibitors currently being tested in clinical trials should be used with caution, at least in tumors in which the NOTCH4 pathway and thus HES1 play a protumorigenic role, as in lung adenocarcinoma." (PMID 37268635, 2023). "Moreover, LOC389641 may activate STAT3 signalling by increasing the expression of EGFR and MET and therefore downregulate cleaved-PARP to inhibit cell apoptosis in lung adenocarcinoma." (PMID 35379783, 2022). "These suggest that ubenimex combined with pemetrexed in lung adenocarcinoma treatment could be therefore achieved by upregulating SOCS1 expression and then inhibiting the JAK2-STAT3 signaling pathway, further confirming the negative regulatory effect of SOS1 on the JAK2/STAT3 signaling pathway." (PMID 35789603, 2022).
lung adenocarcinoma (continued). "ACK1 was also shown to promote the phosphorylation and nuclear localization of STAT3 in cultured human embryonic kidney HEK293T cells and the positive correlation between ACK1 and the levels of tyrosine-phosphorylated STAT3 was validated in primary lung adenocarcinoma (ADC) cells." (PMID 33495411, 2021). "Therefore, in this study, clinical cases and in vitro cell experiments were used to study the effects of lentinan on the proliferation, migration, invasion, apoptosis, and cell stemness of lung adenocarcinoma cells, as well as the involvement of miR-216a-5p and JAK2/STAT3 signaling pathways." (PMID 34900727, 2021). "We found that EGFR expression, STAT3, and the thickness of the stratum corneum (both in millimeters and in number of skin layers) had a statistically significant correlation with an adequate response to treatment with EGFR inhibitors in patients with stage IV lung adenocarcinoma." (PMID 33015988, 2020). "Furthermore, SOCS2 overexpression not only reduced the STAT3 and STAT5 transcriptional activity but also reduced the EMT of lung adenocarcinoma cells, suggesting that SOCS2-modulated STAT3 and STAT5 signalling plays an important role in lung adenocarcinoma migration and invasion." (PMID 29559623, 2018). "Collectively, these results not only suggest that the IL-6/IL-6R/STAT3 may be used as molecular targets for the inhibition of IL-6-induced EMT, but also provide experimental evidence for the potential use of metformin in the treatment of lung adenocarcinoma." (PMID 24789104, 2014). "Since IL-6, through JAK/STAT3 signaling, might be involved in EMT in lung adenocarcinoma, and metformin can inhibit EMT and STAT3 phosphorylation in other cancer types, we hypothesized that metformin might be able to inhibit IL-6-induced EMT and growth and metastasis in lung adenocarcinoma." (PMID 24789104, 2014). "This study proposes that SHP2 may dampen lung adenocarcinoma progression by inhibiting the STAT3/STAT6 pathway in TAMs, consequently reducing M2 polarization and the secretion of factors like cathepsin, which in turn, could limit the growth and spread of lung adenocarcinoma cells." (PMID 38747738, 2024). "Moreover, lack of Stat3 in Kras induced lung adenocarcinoma accelerated tumorigenesis." (PMID 27589562, 2016). "To rule out exclusiveness of the effect of Sestrins on STAT3 in A549 cells, we also silenced SESN2 in another lung adenocarcinoma cell line, H460, and observed upregulation of STAT3 phosphorylation in these cells." (PMID 39985075, 2025). "Depletion of SOCS2 in A549-SOCS2 cells substantially restored the phosphorylation of both STAT3 and STAT5, indicating that both STAT3 and STAT5 activity are primarily subjected to negative regulation by SOCS2 in lung adenocarcinoma cells." (PMID 29559623, 2018).
triple-negative breast carcinoma (192 papers, 2012 to 2026). An invasive breast carcinoma which is negative for expression of estrogen receptor (ER), progesterone receptor (PR), and human epidermal growth factor receptor 2 (HER2). "Suppressor of Cytokine Signaling 3 (SOCS3) is a pivotal negative regulator of the JAK/STAT pathway, and its loss or silencing is frequently associated with hyperactivated STAT3 signaling in aggressive cancers, including Triple-Negative Breast Cancer (TNBC)." (PMID 42077828, 2026). "Studies in triple-negative breast cancer cells have shown that Src/STAT3 signaling cascade is associated with multidrug resistance (MDR)." (PMID 34488773, 2021). "WWOX deficiency leads to the activation of JAK2/STAT3 signaling in metastatic triple negative breast cancer cells." (PMID 34140629, 2021). "Loss of WWOX in triple-negative breast cancer cells leads to activation of the JAK2/STAT3 pathway for metastasis." (PMID 31123603, 2019). "Loss of WWOX upregulates the JAK2/STAT3 pathway for driving cancer metastasis in triple negative breast cancer cells." (PMID 31123603, 2019). "We recently demonstrated that STAT3 knockdown by STAT3 siRNA causes survivin reduction and subsequent cell death in triple negative breast cancer and HNSCC cells." (PMID 29545751, 2018). "Increased STAT-3 activity has also been linked to the development of chemoresistance in triple-negative breast cancer cells (TNBCs) and has been associated with metastasis promotion in TNBC." (PMID 30373171, 2018). "Additionally, expression of STAT3 was suggested to be enriched in triple-negative breast cancer, and negatively associated with lymph node involvement and breast tumor stage in a study based on an in silico network approach." (PMID 26621531, 2016). "In addition, it has been recently shown that estrogen-associated receptor alpha may induce triple-negative breast cancer metastasis as a STAT3 target gene." (PMID 34488773, 2021). "We continue to investigate the contributions of E2F1 and STAT3 to CDK8 inhibitor effects on triple-negative breast cancer cell line MDA-MB-468, and will report our results in due course." (PMID 41596544, 2026). "The inhibitor LLL12B blocks phosphorylation, nuclear localization, and transcriptional activity of STAT3 resulting in suppressing growth and proliferation of triple negative breast cancer cells." (PMID 40354417, 2025). "While the JAK2/signal tranducer and activator of transcription 3 (STAT3) pathway plays a role in tumorigenesis, JAK2/STAT3 inhibitors have shown limited therapeutic efficacy in triple-negative breast cancer (TNBC)." (PMID 40649917, 2025). "Conversely, HLF inhibits ferroptosis by promoting GSH in triple - negative breast cancer cells via the activation of the IL - 6/JAK2/STAT3 axis." (PMID 40371332, 2025). "Phosphorylated STAT3 (Tyr705) has been identified as a biomarker of response predictive of sensitivity to pimozide treatment in triple-negative breast cancer." (PMID 38956591, 2024). "SLSI-1216, a small molecule STAT3 inhibitor, inhibits the proliferation and tumor growth of triple-negative breast cancer cells by inducing apoptosis." (PMID 38872110, 2024). "Recent studies revealed that USP21 affects JAK2/STAT3 axis in triple-negative breast cancer by indirect regulation of JAK2 stability." (PMID 39305962, 2024). "The proto-oncogene MYCL promotes progression of triple negative breast cancers through activation of JAK/STAT3 pathway." (PMID 39545637, 2024). "We determined that ZSW suppresses triple-negative breast cancer cell activity by targeting STAT3 and provides a new compound structure candidate for TNBC clinical drug development." (PMID 37173892, 2023). "For example, a small peptide ASRPS with 60-aa encoded by LINC00908 functions as a potent anti-tumor polypeptide in triple-negative breast cancer by modulating STAT3 activity." (PMID 37285335, 2023).
triple-negative breast carcinoma (continued). "Tocilizumab, for instance, blocks IL6/STAT3 signaling and reduces the cancer/inflammation epigenetic IL6/STAT3/NF-kB positive feedback loop, which is of immense therapeutic utility for patients with resistant triple-negative breast cancer." (PMID 36672697, 2023). "explore the activity of DNA minicircles as a new generation of decoy oligonucleotides capable of targeting the oncogenic transcription factor STAT3 in triple-negative breast cancer." (PMID 35847174, 2022). "Recent results have shown that nintedanib induces apoptosis in triple-negative breast cancer cells by inhibiting the phosphorylation of STAT3 and inhibits the tumor growth of malignant pleural mesothelioma (MPM) via blockade of angiogenesis." (PMID 36055997, 2022). "In particular, previous studies have shown that nintedanib modulates STAT3 activity, resulting in the apoptosis of triple-negative breast cancer cells as well as ameliorates IPF by inhibiting the JAK2/STAT3 pathway." (PMID 36055997, 2022). "In particular, metformin inhibits cell growth, through targeting STAT3, in triple-negative breast cancers." (PMID 36672573, 2022). "For example, STAT3 activation within triple-negative breast cancer led to epithelial-mesenchymal transition (EMT) phenotype and CSC markers expression, and inhibiting STAT3 enhanced the cisplatin sensitivity." (PMID 34975317, 2022). "The phosphorylated STAT3 enters the nucleus and activates the STAT3 signaling pathway to promote metastasis in triple-negative breast cancer (TNBC)." (PMID 35965499, 2022). "Persistent STAT3 signaling plays a pivotal role in human tumor malignancy, including triple-negative breast cancer (TNBC)." (PMID 36009550, 2022). "It is known that nintedanib rescues IPF via regulation of the JAK2/STAT3 pathway and induces apoptosis by inhibiting STAT3 in triple-negative breast cancer cells." (PMID 36055997, 2022). "In triple-negative breast cancer cell lines, pimozide inhibited the STAT-3 mediated activation of matrix metalloproteinase-9 (MMP-9) and vimentin, while in brain tumor cell lines, it induced a STAT-3 mediated apoptosis in vitro and in vivo." (PMID 34944601, 2021). "In this context, metformin was also shown to reduce the signal transducer and activator of transcription-3 (STAT3) phosphorylation at ser-727 and tyr-705 in triple negative breast cancer (TNBC) cell lines, AMPK-dependently." (PMID 34884872, 2021). "Birc5 is also downstream of STAT3 transcription activity in triple-negative breast cancer, and STAT3 binding to the Birc5 promoter has been demonstrated through ChIP analysis." (PMID 33557010, 2021). "The last one is a major anti-apoptotic gene whose expression is induced by STAT3 following exposure to IR in triple-negative breast cancer cells, leading to acquired radioresistance." (PMID 34141616, 2021). "In triple negative breast cancer, the constitutive activation of STAT3 upregulates XRCC1 gene and protein expression levels." (PMID 34067421, 2021). "Treatment with RES decreased acetylated STAT3 in triple-negative breast cancer cells resulted in demethylation and activation of the estrogen receptor-α gene, sensitizing the breast cancer cells to antiestrogens." (PMID 34488773, 2021). "Autophagy was necessary for STAT3 signaling in triple negative breast cancer cells and in starved cancer cells." (PMID 33763424, 2021). "Sequential combination of docetaxel with a SHP-1 agonist enhanced suppression of p-STAT3 signaling and apoptosis in triple negative breast cancer cells." (PMID 33804295, 2021). "The role of STAT3 in the induction and maintenance of CSCs properties has also been investigated in triple-negative breast cancer." (PMID 34141616, 2021). "WWOX prevents phosphorylation of JAK2 and STAT3, and inhibits the transcriptional activity of STAT3 in different TNBC (triple-negative breast cancer) cell lines." (PMID 33946771, 2021).
triple-negative breast carcinoma (continued). "For lung metastasis-free survival of triple-negative breast cancer (N = 166), we observed that high STAT3 activation, high TrkA activation, and high co-activation, were associated with a high likelihood to develop lung metastasis." (PMID 34066153, 2021). "More recently, a phase II clinical trial evaluating a selective JAK1/2 inhibitor in patients with metastatic triple-negative breast cancer (tumors demonstrating p-STAT3 expression) also demonstrated limited clinical efficacy." (PMID 34445170, 2021). "Of the transcription factors showing positive binding, we found STAT3 to be of particular interest due to its prominent role in multiple cancers, including triple negative breast cancer." (PMID 34067421, 2021). "PSD-A significantly inhibited STAT3 activation by suppressing its phosphorylation at tyrosine 705 in both triple positive and triple negative breast cancer cells." (PMID 33013353, 2020). "In another study, radiotherapy resulted in the activation of STAT3 and Bcl-2 in triple-negative breast cancer." (PMID 32872659, 2020). "STAT3 is constitutively activated in triple negative breast cancer, and ample evidence imply that persistently- activated STAT3 maintains constitutive NFKB activity." (PMID 32883235, 2020). "STAT3 is overexpressed and constitutively activated in triple-negative breast cancer cells and contributes to a wide variety of cellular processes involved in cancer progression." (PMID 31671408, 2019). "Aberrant activation of signal transducer and activator of transcription 3 (STAT3) has been documented in various malignancies including triple-negative breast cancers (TNBCs)." (PMID 31058868, 2019). "Autocrine/paracrine activation of IL6 signaling was confirmed by evaluating STAT3 activation in four triple-negative breast cancer model systems." (PMID 31511085, 2019). "In SUM149 triple-negative breast cancer cells, expression of an activated form of STAT3 or an activated form of AKT strongly inhibited the lethality of (ruxolitinib + lapatinib) treatment." (PMID 27379204, 2016). "We have previously published that niclosamide is a potent STAT3 inhibitor in triple negative breast cancer cell lines." (PMID 27888804, 2016). "Both BCL6 and STAT3 play critical roles in triple negative breast cancer, including promoting survival and EMT, through modulating largely distinct target genes." (PMID 26697522, 2015). "Inhibition of BCL6 by siRNA or the peptidomimetic RI-BPI in conjunction with inhibition of STAT3 with the Jak kinase inhibitors TG101348 or nifuroxazide led to enhanced killing of triple negative breast cancer cell lines." (PMID 26697522, 2015). "It has been recently shown in triple-negative breast cancer (TNBC) cells that inhibition of XPO1/CRM1 by selinexor represses survivin transcription by inhibiting STAT3 acetylation." (PMID 25948791, 2015). "Several studies suggest that STAT3 represents a promising molecular target for the prevention of ER-negative and triple-negative breast cancers (TNBC)." (PMID 24743778, 2014). "C188 was tested in vivo in two different triple negative breast cancer human xenograft models in SCID beige mice to determine the effects of Stat3 inhibition alone and in combination with chemotherapy." (PMID 22879872, 2012). "STAT3 is the only gene found to be most methylated in triple-negative breast cancer (TNBC)." (PMID 37737288, 2023). "The results of the present study indicate that SYF regulates the expression of genes involved in cell proliferation, migration, and invasion by regulating the JAK/STAT3 signalling pathway and finally enhances the therapeutic efficacy of paclitaxel in triple-negative breast cancer." (PMID 36678509, 2022). "tDR-0009 induced by hypoxia could be involved in the chemoresistance of triple-negative breast cancer via the regulation of the activation of the phosphorylation of STAT3." (PMID 35456407, 2022).